RNU6-878P (RNA, U6 small nuclear 878, pseudogene)
Gene: Small nuclear RNA gene on chromosome 11 (2,321,718 to 2,321,827, forward strand). Ensembl gene ENSG00000207308.
Homologues: Orthologues: chimpanzee U6 (95% identical), macaque U6 (89% identical), dog U6 (84% identical), rat LOC120097304 (81% identical), mouse Gm55621 (70% identical). Paralogues in human: RNU6-33P (88% identical), RNU6-1 (87% identical), RNU6-116P (87% identical), RNU6-1251P (87% identical), RNU6-15P (87% identical), RNU6-2 (87% identical), RNU6-39P (87% identical), RNU6-3P (87% identical), RNU6-47P (87% identical), RNU6-4P (87% identical), RNU6-5P (87% identical), RNU6-6P (87% identical), and 1287 more.